IL10 (interleukin 10)
Diseases named in the same sentence as IL10 in open-access papers (continued):
Sharing a sentence is not in itself a finding about the gene and the disease.
colitis (continued). "Interestingly, B cells attenuated colitis in an IL10-independent pathway and induced the differentiation of Tregs which supported the functions of IgA-plasma cells." (PMID 37849749, 2023). "Furthermore, HG-9-91-01 treatment decreased colonic TNF-α and IL-12 levels and increased colonic IL-10 production in both colitis models." (PMID 36731029, 2023). "Additionally, higher IL-10 levels have been shown to provide maximum protection against in vivo colitis." (PMID 36832826, 2023). "Polarization of anti-inflammatory IL-10+ macrophages has been shown in a colitis model, and neuroprotective effects in spinal cord injury, as well as improved wound healing, were associated with MCP-1-dependent recruitment of macrophages and their polarization towards a reparative phenotype." (PMID 37626914, 2023). "Reassuringly, IL-10 serum levels and their expressions in T cells were restored in colitis mice when they underwent late onset tofacitinib treatment although tofacitinib had been shown to completely abolish the expression of this STAT3-dependent cytokine in culture." (PMID 37275854, 2023). "The development of spontaneous colitis in IL-10-deficient mice is not observed under germ-free conditions." (PMID 37239894, 2023). "Thus, we measured the fecal levels of this miRNA before and during severe colitis and observed an increase in fecal miR-21, but only in female IL-10−/− mice." (PMID 37373511, 2023). "Furthermore, the probiotic formulation including Bifidobacterium and Lactobacillus reduced the severity of experimental colitis by inducing Treg cell population in MLNs, while concurrently increasing IL-2, IL-4, and IL-10 expression." (PMID 37110390, 2023). "By contrast, in penk-deficient chimeric mice, bacteria infiltrate the mucus until the vicinity of the epithelial lining although the mucus thickness was not decreased, as already reported at the onset of the DSS-induced colitis and in IL-10−/− mice with low grade of inflammation." (PMID 37968381, 2023). "However, after 6 days, the colitis regressed, which was accompanied by an increase in colonic IL-10 levels." (PMID 37727785, 2023). "Protection from colitis in IL-10cKO mice was associated with an expanded population of IL-10–producing type 1 Tregs (Tr1, CD4+Foxp3−) in the colonic lamina propria that produced more IL-10 on a per-cell basis compared with wild-type intestinal Tr1 cells." (PMID 37314833, 2023). "However, B. bifidum BGN4-pBESIL10 had little effect on IL-10 production and the improvement of colitis." (PMID 37485519, 2023). "Herein, we characterized a Betaretrovirus infection in the IL-10−/− model of colitis, which is endemic in laboratory mice, replicates in the mucosal lymphocytes using a viral superantigen mechanism, and subverts immune responses by triggering the production of IL-10." (PMID 36869359, 2023). "One of the issues with the mucus barrier in IBD patients is the phenomenon of mucin protein misfolding and a study done in an animal model of spontaneous colitis revealed that IL-10 administration can preserve mucin protein folding and mucus secretion by goblet cells." (PMID 38107848, 2023). "In Caco2 cells, docosahexaenoic acid (DHA) limited the effect of the inflammatory stimulus on occludin, ZO-1 and barrier function, inhibited the NF-kB pathway and ameliorated experimental colitis in IL-10-/- mice, improving intestinal epithelial barrier function." (PMID 36839239, 2023). "Moreover, a positive correlation was observed between Alloprevotella and the anti-inflammatory cytokine IL-10 in mice with DSS-induced colitis, indicating a potential link to the protective effect against inflammation." (PMID 37185924, 2023). "Through the induction of IL-10, S. cholersesuis carrying the IL-19 gene may have therapeutic potentials for treating murine colitis." (PMID 37375032, 2023).
colitis (continued). "Contrastively, female IL-10−/− mice had very pronounced microbiota shifts that could be clearly clustered before colitis (D0) and during mild colitis (D42) and severe colitis (D91)." (PMID 37373511, 2023). "In addition, the levels of oxidative stress (MPO, SOD, and MDA) and inflammatory cytokines (TNF-α, IL-1β, IL-6, and IL-10) were reversed by PHI in colitis mice." (PMID 36768559, 2023). "In vitro and in vivo studies showed that L. plantarum LS/07 activated IL-10 production in macrophages derived from blood monocytes and improved weight loss and diarrhea signs of colon inflammation in dextran sulphate sodium (DSS)-induced colitis rat models." (PMID 36986118, 2023). "Indeed, the intragastric administration of Lactococcus lactis, which secrete IL-10, reduces or prevents the dextran sulfate sodium- (DSS) induced colitis in IL-10 deficient mice." (PMID 37106999, 2023). "We found that, upon DSS‐induced colitis, CD11b+ F4/80+ adipose tissue macrophages (ATMs) are one of the major cell populations producing IL‐10 in visceral adipose tissues, whereas IL‐10 production in T and B cells were unaltered." (PMID 36795015, 2023). "In addition, live probiotic L. johnsonii suppressed TNF and IL-1β expression and stimulated anti-inflammatory cytokine (IL-10) expression in the colon of trinitrobenzenesulfonic acid (TNBS)-induced colitis mice." (PMID 36986118, 2023). "We further explored the in vivo functions of circPRKAR1B using IL‐10‐KO mice as the colitis model." (PMID 37679886, 2023). "Defects in IL‐10 signalling leads to early‐onset colitis and Crohn’s disease." (PMID 35246947, 2023). "In addition, the reduction of anti-inflammatory cytokines such as IL-10 can further amplify intestinal vascular permeability induced by IFN-γ in experimental colitis." (PMID 36982601, 2023). "Regulated the colitis gut microbiota, protected the mucosal barrier system, improved the antioxidant levels, decreased the weight loss and DAI, reduced the expression of TNF-α, up-regulated the expressions of IL-10." (PMID 37485519, 2023). "Additionally, the DSS treatment dramatically decreased the colonic level of IL-10 in the colitis mice compared to that of the mice in the NC group (p < 0.01)." (PMID 37762155, 2023). "However, 0.1% CUR demonstrated protective effects against colitis and decreased NF-kB activation in colonic epithelial cells only in IL-10−/− mice." (PMID 36677021, 2023). "Furthermore, the administration of emulsifiers at a low concentration leads to low-grade inflammation and obesity/metabolic syndrome in wild-type mice, while it promotes colitis in IL-10−/− mice." (PMID 37238805, 2023). "Also, stimulation of canine MSCs with TNFα elevates TSG-6 and PGE2 resulting in in vivo benefit by regulating colonic inflammatory cytokines such as IL1β, IL6, and IL10, and ameliorating induced colitis in mice." (PMID 37275605, 2023). "The IL-10 signaling axis is an important regulator in colitis." (PMID 36767519, 2023). "Viable Klebsiella variicola in Enterobacteriaceae is isolated exclusively in CD‐MAT and can induce a pro‐inflammatory response in vitro and exacerbates colitis both in dextran sulfate sodium (DSS)‐induced colitis mice model and IL‐10−/− spontaneous colitis mice model." (PMID 36802200, 2023). "Additionally, they have been shown to modulate the expression of anti- and pro-inflammatory cytokines in the colon and plasma of colitis models and have a higher ability to suppress IL-6 and increase IL-10 levels than wild-type probiotics." (PMID 37049407, 2023). "However, in previous work, Foxp3-specific deletion of IL-10 resulted in only modest colitis compared with the severe colitis observed in IL-10KO mice." (PMID 37314833, 2023). "Bacteria of this genera were found to produce short chain fatty acids (SCFA), regulate immunity in multiple sclerosis through IL-10 induction, and relieve intestinal inflammation in mice with acute and chronic colitis by reducing the levels of pro-inflammatory cytokines." (PMID 37948383, 2023).
colitis (continued). "Additionally, both niacin and butyrate acid can prevent colitis and colon carcinogenesis by upregulating anti-inflammatory molecules secreted by monocytes, promoting differentiation of Treg cells and interleukin-10 (IL-10)-producing T cells." (PMID 38149240, 2023). "In order to detect whether paroxetine could regulate PGE2, INF-γ, IL-1β, and IL-10 levels in mice with DSS-induced colitis, ELISA was used to examine the levels of PGE2, INF-γ, IL-1β, and IL-10 in LPMCs." (PMID 37242446, 2023). "Additionally, more mechanistic insight has been gained by studies showing that Alistipes abundance is sufficient to induce colitis in IL10-/- mice and can lead to tumorigenesis." (PMID 37190186, 2023). "Pharmacological NR1D1 activation represses pro-inflammatory cytokine secretion and promotes IL-10 in primary rat microglia, in murine models of colitis, in the lungs of murine models of inhaled LPS, in the livers of murine models of fulminant hepatitis, and in murine and human macrophages." (PMID 36860863, 2023). "Additionally, TIMP-1 is expressed in colitis lesions and is involved in the production of the proinflammatory cytokine IL-10." (PMID 37375714, 2023). "Further analysis demonstrated that MSCs-secreted thrombospondin-1 (THBS1) may boost IL-10 + Bregs and control the development and recurrence of colitis." (PMID 36707899, 2023). "However, the content of IL-10 was significantly increased in colitis mice, which was similar with the previous study." (PMID 36768559, 2023). "The reason of higher levels of IL-10 in colitis mice may be seen as a compensatory mechanism for colitis damage." (PMID 36768559, 2023). "In 2000, a natural probiotic, Lactococcus lactis, was genetically modified to constitutively secrete the human anti-inflammatory cytokine protein interleukin-10 (IL-10); when orally administrated in rat models of colitis, a significant reduction of inflammation was assessed." (PMID 37237771, 2023). "Seven hub genes IL10, IL4, IL6, IFNG, IL1B, TNF and IL17A might be responsible for causing Colitis and Arthritis, except for Rheumatoid Arthritis." (PMID 36989283, 2023). "In contrast, PPs in mice with DSS colitis contained more regulatory CD11b+ B-cells compared to healthy control mice, which had a protective effect on disease progression and displayed an IL-10-mediated immunosuppressive function that was dependent on hypoxia-inducible factor-a (HIF-1a) expression." (PMID 35163775, 2022). "Nicotinamide could restore valeric acid and IL-10 levels (i.e., increasing them) in a mouse colitis model." (PMID 36235651, 2022). "Similarly, some studies also found that butyrate increased the levels of Treg cells, IL-10 and IL-12 in peripheral blood of mice, decreased the levels of IL-17 in plasma and colon mucosa and thus improved colitis in mice." (PMID 36189293, 2022). "In addition, IL-10−/−/β7−/− mice had significantly higher histological indices of colitis, while the ileum was mostly uninvolved." (PMID 34433904, 2022). "In Il10−/− mice, Enterococcus faecalis promotes colitis development and colorectal tumorigenesis." (PMID 35967333, 2022). "Notably, spontaneous colitis induction in toll-like receptor (TLR)-5 and IL-10 knockout mice has been associated with an expansion of Proteobacteria." (PMID 35693794, 2022). "Whereas the prior study employed mice on a mixed 129 and C57BL/6 background, which was apparently susceptible to colitis caused by the absence of IL10, our study used C57BL/6 mice, which were congenic for the Cdcs1 IBD susceptibility loci." (PMID 35013585, 2022). "EVs decreased NF-κB levels and mRNA levels of TNFα, IL-1α, IL-1β and IL-2, and increased mRNA levels of TGFβ and IL-10 in LPS-induced inflammation in human intestinal epithelial cells (HT-29) and reduce inflammation symptoms of dextran sulfate sodium-induced colitis in mice." (PMID 35432276, 2022).
colitis (continued). "Indeed a role of α4β7 for intestinal recruitment of Tregs has been proposed, and Treg blockade leads to worse colitis in IL-10−/− mice." (PMID 34433904, 2022). "Thus, the transfer of IL10-secreting B cells can rapidly exert a protective effect during an acute model of chemically-induced colitis." (PMID 35082296, 2022). "IL-10 can suppress the bactericidal response of immune cells against S. Typhimurium, and its reduction promotes a defensive reaction but leads to the development of colitis." (PMID 35658572, 2022). "However, pDCs stimulated by a gut commensal molecule show anti-inflammatory effects on 2,4,6-trinitrobenzene sulfonic acid (TNBS)-induced Th1-type colitis by driving IL-10 production by CD4+ T cells." (PMID 34997096, 2022). "The inhibitory cytokine, IL-10 produced by Treg cells, antagonises the development of colitis." (PMID 35734396, 2022). "Moreover, co-administration resulted in a significant increase in the anti-inflammatory cytokine IL-10, which can aid in the treatment of colitis." (PMID 35688918, 2022). "IL-10 is an important cytokine for inhibiting colitis which is secreted by Treg cells." (PMID 36189293, 2022). "Indeed, the lack of mTOR signalling specifically in DCs resulted in the suppression of IL-10 production by cDC2 and a higher susceptibility to dextran sodium sulfate (DSS)-induced colitis." (PMID 36189323, 2022). "The addition of CMC also induced severe CD-like colitis in IL10 KO mice." (PMID 35893902, 2022). "AOS-M and AOS-H treatment could downregulate the IFN-γ level and upregulate the anti-inflammatory cytokine IL-10 level in the serum of DSS-induced colitis mice (p < 0.05), suggesting that AOS also have anti-inflammation ability in vivo." (PMID 35889822, 2022). "(10 g/kg, concentrated water decoction) could protect against the acetic acid and dinitrochlorobenzene-induced colitis in a rat model by regulating the levels of IL-2, IL-10, and IL-17 cytokines in serum." (PMID 36160392, 2022). "Besides, supplement of SCFAs producing bacteria has been found to produce a protein which inhibits the NF-κÂ pathway, to stimulate production of IL-10 and to be able to inhibit experimental colitis in mice." (PMID 35495685, 2022). "Furthermore, IL-10 production from macrophages in the small intestine is necessary for protecting intestinal health from colitis by means of C. butyricum." (PMID 35844624, 2022). "Moreover, L. acidophilus NCFM and FAHWH11L56 showed similar effects on various indicators of DSS-induced colitis, increasing the IL-10 and IL-17 in the colon, and modifying the CCL2/CCR2 axis and CCL3/CCR1 axis." (PMID 36499169, 2022). "Mice that are deficient for β7 have a functional impairment that involves both αEβ7 and α4β7 integrins, either of which may be responsible for the worsening of colitis observed in IL-10−/−/β7−/− mice." (PMID 34433904, 2022). "Colitis-related parameters such as tissue damage, reduction in goblet cell numbers as well as immune cell infiltration in colon were significantly elevated in IL-10−/− mice and lowered by resveratrol treatment." (PMID 35163137, 2022). "Lactococcus lactis-secreting IL-10, elafin (a human protease inhibitor), and IL-27 (an immunosuppressive cytokine) reportedly have anti-inflammatory effects in colitis models and may therefore represent potential candidates for future clinical trials." (PMID 35408838, 2022). "To determine if the reduced motility of PMNs in the inflamed mucosa observed after induction of colitis by DSS was model specific, we examined PMN trafficking in another model of colitis induced by blocking IL-10 signaling and oral inoculation with Helicobacter hepaticus." (PMID 36712325, 2022). "Hence, the further applicability of EcN-Elafin for treating IBD patients requires future studies in other colitis models (e.g., IL-10 knockout and TNBS-induced colitis)." (PMID 35602072, 2022). "Thus, anti-p40 mAb effectively mitigates colitis in IL-10−/− animals from our breeding colony, as previously reported." (PMID 35900107, 2022).
colitis (continued). "Gavage L. johnsonii could alleviate colitis by specifically increasing the proportion of intestinal macrophages and the secretion of Il-10 with macrophages depleted model and in Il10−/− mice." (PMID 36398889, 2022). "On the other side, cinnamon extract and nobiletin showed clearer effects on the attenuation of symptoms in the pathology of colitis in IL-10−/− mice than resveratrol; nonetheless, similar to resveratrol, nobiletin also delayed the onset of symptoms in affected animals during the experimental course." (PMID 35163137, 2022). "Furthermore, mPGES-1−/− mice showed higher expression of colonic IL-10 (an anti-colitis cytokine also produced by Tregs)." (PMID 34983695, 2022). "IL-10 inhibits IFN-γ production by Th1 cells and reduces Th17 responses in the DSS model, and mice with IL-10-deficient Treg develop spontaneous colitis." (PMID 35741032, 2022). "In contrast, it has previously been reported that the absence of CCR2 in IL10-deficient mice did not influence colitis severity." (PMID 35013585, 2022). "This can be interpreted as IL-10 induced promotion of an anti-inflammatory response in colitis mucosa confounded with obesity, while the combination of SW and IAP treatment affording intestinal protection resulted in a downregulation of this cytokine in intestinal mucosa." (PMID 35328382, 2022). "Although inulin could present positive effects on inflammation, there are several studies that have shown that it exacerbates the severity of colitis in an IL10-/- and DSS model of colitis and facilitates the progression of hepatocellular carcinoma in mice." (PMID 36432460, 2022). "Furthermore, we assessed the potential therapeutic effect of mannose treatment on IL-10−/− spontaneous colitis model mice." (PMID 35974017, 2022). "L. johnsonii could activate native macrophages into CD206+ macrophages and release IL-10 through TLR1/2-STAT3 pathway to relieve experimental colitis." (PMID 36398889, 2022). "In addition, the anti-inflammatory cytokine IL-4, IL-10 secreted by Th2 cells showed a distinctive reduction in the serum and colonic tissues of the colitis mice (M−N)." (PMID 35372817, 2022). "Several in vivo studies indicated that anti-CXCL10 antibodies could inhibit epithelial ulceration in a UC murine model, attenuate inflammation in IL10−/− mice, and reduce colitis by compromising T helper type 1 (Th1) induction and recruitment." (PMID 36003333, 2022). "Q-PCR analysis showed that DSS-colitis-induced up-regulated mRNA expression of Cgas, Il10, Ifnb1, Tnf, and Il1b was significantly reduced in STING deficient mice (For Cgas: p < 0.01; For Il10: p < 0.01; For Ifnb1: p < 0.001; For Tnf: p < 0.001; For Il1b: p < 0.001)." (PMID 36467059, 2022). "Mice with induced colitis were subjected to forced moderate exercise, which led to an increase in cytokines such as Tnf, Il1b, and Il10 in the colon and exacerbated colitis symptoms, whereas 30 days of VWR attenuated colitis in these mice and was associated with a decrease in Tnf." (PMID 35159375, 2022). "Next, in order to understand the mechanisms behind the acceleration of colitis in IL-10−/−/β7−/− mice, we first tested the hypothesis that it was due to inadequate regulatory control at the intestinal mucosa." (PMID 34433904, 2022). "Lactobacillus helveticus NS8 has a good binding ability to human intestinal epithelial cells, which could promote the secretion of anti-inflammatory cytokine IL-10, and showed a considerable preventive effect on colitis in mice." (PMID 36118769, 2022). "Interleukin-10 knockout (IL10KO) mice were fed diets supplemented with MDX or carboxymethyl cellulose (CMC) to determine their impact on colitis onset and severity; microbiome composition, function, and location; colonic immune cell infiltrates; and mucus layer integrity." (PMID 35359925, 2022). "Our data suggest that UCC118TM promotes recovery from colitis in an IL-10 independent mechanism." (PMID 35889102, 2022).